FGF21 (fibroblast growth factor 21)
Diseases named in the same sentence as FGF21 in open-access papers (continued):
Sharing a sentence is not in itself a finding about the gene and the disease.
Obesity (continued). "Individuals with T2D and obesity after RYGB presented with increased serum FGF-19 levels (p = 0.024) and decreased total bile acid (p = 0.01) and FGF-21 levels (p = 0.005)." (PMID 41155711, 2025). "Furthermore, we explore the interrelationship between BCAAs and FGF21 as critical biomarkers of metabolic health and aging, providing new insights into metabolic adaptations that may inform therapeutic strategies for obesity‐related disorders." (PMID 41117265, 2025). "There is also a recent bi-directional Mendelian randomization study supporting that FGF-21 was negatively regulated by NAFLD, whereas positively regulated by obesity and T2DM." (PMID 40465044, 2025). "Further studies would be necessary to understand the implications of the changes in FGF21 and GDF15 after bariatric surgery, which follow a different pattern, in relation to the improvement of obesity and the resolution of T2D." (PMID 40377893, 2025). "Our findings support that obesity, T2D, and aging increase the concentrations of both GDF15 and FGF21." (PMID 40828431, 2025). "Fibroblast growth factor 21 (FGF21), a liver hormone, is known to regulate adaptation to metabolic stress, including high-calorie diets that induce obesity." (PMID 39596499, 2024). "Ongoing investigations into gene therapy to elevate FGF21 activity in humans consider it a promising therapeutic approach for the treatment of type 2 diabetes (DM2) and obesity." (PMID 38203812, 2024). "Our study revealed that irisin, FGF21 and NRG4 levels of two groups with metabolically healthy and unhealthy obesity, which were matched in terms of age, gender, BMI, fat, muscle, lean body mass, fat, and muscle distribution were similar to each other." (PMID 39008201, 2024). "Thirdly, FGF21 also stimulates GABA-containing neurons in the lateral hypothalamic region and zona incerta to protect against obesity." (PMID 39062868, 2024). "Therefore, it has been speculated that the unchanged postprandial levels of adiponectin in obese individuals after the experimental fat could be explained, considering that the FGF-21-adiponectin axis is overruled in obesity, is perhaps due to FGF-21 resistance." (PMID 38256185, 2024). "FGF21 is known to enhance whole body metabolism by inducing browning of SAT, thereby providing protection against diet-induced obesity." (PMID 38960128, 2024). "Our findings affirm that SLC25A28 overexpression contributes to increased weight gain and accelerates the occurrence of obesity, as mice with SLC25A28 overexpression manifested an increase in adipocyte size and serum adiponectin, while serum FGF21 decreased." (PMID 38736904, 2024). "The therapeutic application of FGF21 extends to carbohydrate and fat metabolic disorders, including type 2 diabetes mellitus (T2DM) and obesity." (PMID 38902808, 2024). "In this study, we found that the abundance of the genus Paramuribaculum, including the species Paramuribaculum intestinale, was negatively correlated with FGF21 in BDL mice, which is regarded as a promising intervention therapy for obesity." (PMID 39391493, 2024). "As such, subjects with obesity and non-alcoholic fatty liver disease (NAFLD) have increased systemic FGF21 levels and hepatic mRNA expression, suggesting an “FGF21 resistant” status, although this remains contentious." (PMID 37432218, 2023). "Subjects with obesity showed significantly higher values of NOV/CCN3, leptin and FGF21, and significantly lower values of adiponectin than normal-weight subjects." (PMID 38137540, 2023). "Interestingly, an FGF-21 resistant state in obesity could be another reason." (PMID 37436597, 2023). "There are significant differences in body composition as well as concentrations and function of adipokines, such as leptin, adiponectin, and FGF21, between pregnant women with a history of RYGB, women with obesity, and normal-weight controls." (PMID 37299461, 2023).
Obesity (continued). "For example, the presented data of treatment with FGF-21 agonists or FGF-19 antibodies or analogues showed the great potential for their use in metabolic diseases, such as obesity, through beneficial effects on IS, lipid levels or food intake." (PMID 37239098, 2023). "Mechanisms of FGF21 against T2DM include improving glucose homeostasis, attenuating obesity, and alleviating inflammation." (PMID 36594101, 2023). "FGF21 can improve the development of CVMDs, including atherosclerosis, CAD, MI, H/R injury, HF, T2DM, obesity, and NASH, in vivo and in vitro." (PMID 36594101, 2023). "In contrast, liver-specific FGF21 knockout (FGF21 LKO) completely reversed OVX-induced high GCs and high visceral adipose Hsd11b1 expression, thus abrogating OVX-induced obesity in females." (PMID 37834368, 2023). "A study in people living with obesity and T2DM demonstrated that the expression of genes comprising the FGF-21 signaling pathway was also lower in visceral fat than in subcutaneous fat." (PMID 37436597, 2023). "Surprisingly, however, individuals with metabolic disorders such as obesity, T2DM and fatty liver have high levels of FGF21 and respond poorly to exogenous FGF21, this phenomenon was defined as FGF21 resistance." (PMID 37424900, 2023). "Specifically, the FGF-21 analogue pegbelfermin (BMS-986036), has been shown to improve not only metabolic markers, but also liver fibrosis in patients with obesity and T2D." (PMID 37239098, 2023). "Conversely, as in OPA1 BKO mice, long-term induction of GDF15 attenuated progression of obesity by increasing energy expenditure in DIO, while FGF21 was dispensable for this phenotype." (PMID 37819027, 2023). "Further, to improve efficacy and safety of FGF-21-based therapeutic strategies and with regard to a possible AT selective FGF-21 resistance in states of obesity, the development of tissue specific analogues has to be discussed." (PMID 37239098, 2023). "Serum FGF21 levels are significantly increased in individuals with T2DM and obesity, which can be deleterious for sarcopenic individuals with physical frailty." (PMID 37153220, 2023). "Fibroblast growth factor-21 (FGF-21) is a novel metabolically active hormone that has been investigated, given its potential therapeutic role in obesity and metabolic recovery following bariatric surgery, particularly for diabetes." (PMID 36462120, 2023). "The aim of this study was to compare the effects of FGF21 on body weight, food preferences and glucose and lipid metabolism in C57Bl/6J male and female mice with SFD-induced obesity." (PMID 37469453, 2023). "Other genes therapies investigated for obesity include Follistatin (FST), Fibroblast growth factor 21 (FGF21), Adipose-derived mesenchymal stem cells (ADMSCs), and CRISPR-Cas9-based gene editing system." (PMID 37712012, 2023). "In subjects with obesity and/or type 2 diabetes and NAFLD, FGF21 circulating levels are higher than those measured in healthy age–matched subjects." (PMID 37274345, 2023). "A previous study in diet-induced obesity mice demonstrated that there was decreased expression of the FGF-21 receptor in white adipose tissue and after FGF-21 administration, the reduction in plasma glucose was attenuated, compared to lean ones." (PMID 37436597, 2023). "In agreement with previous studies, FGF-21 quartiles were positively correlated with diabetes indicators (FPG), obesity indicators (BMI, WC, HC and WHR), hypertension indicators (SBP and DBP) and dyslipidemia indicators (TG) in this study." (PMID 37658393, 2023). "Three proteins (C1QTNF1, FGF-21 and CST3) were associated with incident HF among patients without bariatric surgery who retained excess body fat, suggesting that dyslipidemia and chronic kidney disease may constitute therapeutic targets to prevent the development of HF among patients with obesity." (PMID 35945262, 2022).
Obesity (continued). "Previous studies reported there is an increase of FGF21 levels in cardio-metabolic conditions such as CAD, heart failure, atrial fibrillation, MI, obesity, and diabetes mellitus." (PMID 36180826, 2022). "Metformin suppresses adipocyte differentiation by increasing FGF21 expression in the liver and white adipocytes in an AMPK-independent way, thus eliciting its therapeutic effect on T2DM, obesity and fatty liver." (PMID 36484892, 2022). "Fibroblast growth factor-21 (FGF-21) is one of the most important growth factors and plays an important role in the pathogenesis of metabolic diseases such as obesity and diabetes." (PMID 36712965, 2022). "In addition, FGF21 might inhibit hepatic expression of sterol regulatory element-binding protein 2 and increase adiponectin levels, then effectively improved atherosclerosis and prevented obesity-related metabolic heart disease." (PMID 35909513, 2022). "Recent studies demonstrate that the fibroblast growth factor-21 (FGF21), an hepatokine, is partly responsible for the beneficial actions of an exogenously administered NRG1 fusion protein on obesity-related metabolic outcomes." (PMID 35220393, 2022). "Myokines affecting sarcopenic obesity include IL-6, IL-10, IL-15, myostatin, insulin-like growth factor (IGF-1), irisin, FGF-21, and leukemia inhibitory factor (LIF)." (PMID 35250869, 2022). "Melatonin suppressed obesity and insulin resistance resulting from the HFD by enhancing BAT activity and energy expenditure, and these effects were dependent on FGF21." (PMID 36207302, 2022). "Our results demonstrate that targeting Mat1a promotes the secretion of FGF21 in both, DIO and genetically induced obesity (ob/ob mice) models." (PMID 35232994, 2022). "Elevated circulating levels of FGF-21 in insulin resistance states like obesity, type 2 diabetes, and NAFLD suggests an impairment and resistance to the actions of FGF-21." (PMID 35745238, 2022). "These events appear to affect myokines that are effective in sarcopenic obesity such as IL-6, IL-10, IL-15, myostatin, insulin-like growth factor (IGF-1), irisin, and fibroblast growth factor-21 (FGF-21)." (PMID 35250869, 2022). "For this purpose, in rats with obesity induced by a high-calorie diet (HCD), we determined the serum concentration of the two new hormones—FGF-19 and FGF-21—whose role in the pathogenesis of obesity is suggested, but not yet established." (PMID 36362225, 2022). "In skeletal muscle, although the basal expression of FGF21 is low, FGF21 expression is strongly induced by the forced activation of PERK; this can help prevent obesity." (PMID 35159314, 2022). "After induction of obesity, female C57BL/6N mice received a 7-day course of subcutaneously administered FGF21." (PMID 36406708, 2022). "In a mouse model of adipocyte specific defect in oxidative phosphorylation (OXPHOS) both FGF21 and GDF15 were found to be induced and both were shown to be instrumental in protection from obesity and insulin resistance induced by high fat diet feeding." (PMID 33464381, 2021). "Several studies with mouse models of obesity and T2DM consistently showed that FGF21 administration reduces body mass, body fat mass and fat content in the liver." (PMID 34517929, 2021). "Overall, hepatokines including FGF-21, Fetuin-A, ANGPTL4, and follistatin can ameliorate metabolic disorders and lipogenesis in obesity and T2D." (PMID 33498410, 2021). "A variety of analogues and mimetics for FGF21 and GDF15 have been investigated for treatment of obesity." (PMID 34777390, 2021). "Conversely, FGF21 derives from WAT and pancreas during overfeeding and obesity-inducing conditions, from BAT during cold exposure, and from skeletal muscle during exercise." (PMID 35046901, 2021).
Obesity (continued). "Thus, FGF21 may represent a novel therapeutic molecule based on the findings that it protects animals from diet-induced obesity and reduces hepatic lipid accumulation, enhances glucose metabolism, and thus prevents hepatic steatosis, fibrosis, and NAFLD when administered to diabetic rodents." (PMID 33785868, 2021). "The aim of this study was to assess whether the effects of FGF21 administration on glucose and fat metabolism, choice between standard and high-fat diets, and the expression of hypothalamic neuropeptides regulating food intake depend on sex in mice with diet-induced obesity." (PMID 34638898, 2021). "FGF21 has beneficial pharmacological effects on T2DM, obesity, and NAFLD, and a large number of preclinical studies have been reported." (PMID 33869312, 2021). "Taken together, FGF21 functions, at least in part, to offset the vulnerability that is incurred by oncogenic KRAS and hijacked by obesity and other inflammatory states." (PMID 33668583, 2021). "Elevated levels of FGF21 (both circulation and mRNA) have been observed in cases of several metabolic disorders (NAFLD, obesity, T2DM), which suggests protective activities against those diseases." (PMID 34203309, 2021). "Another PEGylated FGF21 analogue, pegbelfermin, has been tested in a phase 2a study on NAFLD patients with obesity." (PMID 34203309, 2021). "Several recently discovered batokines, such as FGF21, NRG4, BMP8b, CXCL14, or adiponectin have been shown to exert a protective role against obesity by enhancing beiging of WAT, lipolysis, sympathetic innervation, or polarization of M2 macrophages." (PMID 34708041, 2021). "FGF21 transgenic mice fed high-fat, high-carbohydrate (HFHC) food are resistant to weight gain and obesity." (PMID 33869312, 2021). "The same effect was observed in FGF21-treated New Zealand obese (NZO) mice, which were a model for polygenetic obesity and type 2 diabetes." (PMID 34943946, 2021). "Although CREBH is upregulated in liver and Fgf21 production is increased by obesity, the capacity of the CREBH–Fgf21 axis to mitigate weight gain and obesity-related metabolic disorders is limited under natural conditions." (PMID 34023388, 2021). "As FGF21 acts as endocrine hormones and take part in the regulation of glucose and lipid metabolism 16, pharmacological application of FGF21 holds great promise as effective therapeutic means for treating NASH), obesity and diabetes." (PMID 34326695, 2021). "Finally, administration of recombinant FGF-21 in rodents and humans improves the lipid profile and insulin sensitivity, indicating that this analogue may be useful in the pharmaceutical management of the complications of obesity and insulin resistance." (PMID 33924457, 2021). "Administration of exogenous FGF21, FGF21 analogs, or FGFR1-KLB agonists promotes an array of metabolic benefits in mice that intercept obesity, type 2 diabetes, fatty liver disease, and hyperlipidemia." (PMID 33668583, 2021). "Moreover, FGF-21 is an independent predictor of the metabolic syndrome and diabetes in healthy Caucasians40 and correlates positively with obesity where paradoxical increase of serum FGF-21 in obese individuals may be explained by a compensatory response or resistance to FGF-2141." (PMID 32404980, 2020). "It was previously shown that adult patients with obesity and metabolic diseases present reduced serum FGF19 levels with compensatory increases in FGF21 concentrations." (PMID 32546231, 2020). "For example, the method clearly picks up fibroblast growth factor 21 (FGF21), a hormone that is known to have elevated levels in insulin-resistant morbidities such as obesity and T2DM." (PMID 33204460, 2020). "Opposite to plasma FGF21, fasted serum FGF19 levels are reduced in individuals with overweight, obesity and NAFLD." (PMID 33414764, 2020).
Obesity (continued). "Increased levels of adiponectin in non-human primates and humans with metabolic disease (type 2 diabetes, obesity and NASH) have been consistently observed following treatment with various FGF21 analogs." (PMID 33381084, 2020). "While mild cold exposure is essential to trigger FGF21 release in UCP1-KO mice, FGF21 only unfolds its anti-obesity effect in combination with overnutrition in the form of high-fat diets." (PMID 32714278, 2020). "In this study, we enrolled 78 patients with obesity and evaluated the change of BDNF and FGF21 6 months after LSG." (PMID 32210348, 2020). "In conclusion, the present study suggests that increase in FGF21 serum levels can contribute to preservation of FFM and RMR after interdisciplinary therapy to WL in adolescents with obesity." (PMID 32267352, 2020). "Interestingly, FGF-21 was similarly decreased by both exercise programs in HFD groups, as a change that could indicate that exercise induces a systemic sensitization to the action of this molecule, considering that obesity it has been reported as an FGF-21 resistant state." (PMID 31105582, 2019). "Thus, we propose that FGF21 could be a key mediator of the developmental programming of obesity." (PMID 29434210, 2018). "It has been reported that the chronic administration of FGF21 improved HDL cholesterol levels and reduced LDL cholesterol levels in rhesus monkeys and humans with diabetes and obesity." (PMID 30157856, 2018). "This is because FGF-21 and GDF-15 have also been found elevated in other conditions, such as diabetes, hepatopathy, renal insufficiency, malignancy, or obesity." (PMID 29385732, 2018). "The endocrines FGF19, FGF21, and FGF23, have great potential to be important therapeutics for a variety of human diseases such as obesity, type II diabetes, and kidney and cardiovascular diseases." (PMID 30068552, 2018). "Because of this obvious contradiction, we aimed to confirm in a model for polygenic obesity and diabetes, the New Zealand obese (NZO) mouse, the beneficial effects of FGF21 that have been observed in other models." (PMID 28770320, 2017). "If having high FGF-21 levels benefit mitochondrial patients, the FGF-21 analogue that has been trialled as a drug treatment for hyperglycaemia and obesity would also have potential as a therapy for MD." (PMID 28825656, 2017). "In a recent clinical trial, treatment with an analog of fibroblast growth factor 21 (FGF21), a representative hepatokine, produced significant improvements in dyslipidemia in humans with obesity and type 2 diabetes." (PMID 28376109, 2017). "Recently, an FGF21 analog, LY2405319, has been developed and used in a randomized, placebo-controlled, double-blind trial in patients with obesity and type 2 diabetes." (PMID 27498701, 2016). "In mice with diet induced obesity (DIO), FGF21 mRNA expression was 4-fold higher than that seen in lean animals (Lean Fed 0.22 ± 0.04; DIO fed 1.0 ± 0.23; p = 0.02) and a 50% fall was observed with fasting." (PMID 26872145, 2016). "Moreover, the inter-organ cross-talk secretion from the hepatic FGF21 to adipocytes leads to the correction of deranged glucose, lipid and energy metabolism which benefit the organism during stress-induced pathologies such as obesity, diabetes, fatty liver and infection." (PMID 27358750, 2016). "Increased plasma FGF21 levels and hepatic expression in KD-fed mice is probably secondary to hepatic fat accumulation and may represent a compensatory mechanism to counteract hepatic insulin resistance, similar to what is seen in patients with obesity, type 2 diabetes and NAFLD." (PMID 25973847, 2015). "Markers related to endothelial function and angiogenesis found to be raised in GDM after adjustment for confounders including obesity include tissue plasminogen activator (TPA), fibroblast growth factor-21 (FGF-21) and glycosylated fibronectin." (PMID 26110385, 2015).